CD226 (CD226 molecule)
Diseases named in the same sentence as CD226 in open-access papers (continued):
Sharing a sentence is not in itself a finding about the gene and the disease.
acute leukemia (3 papers, 2019 to 2021). A clonal (malignant) hematopoietic disorder with an acute onset, affecting the bone marrow and the peripheral blood. "Relevant for antileukemia activity, DNAX accessory molecule 1 (DNAM-1) (CD226) can recognize the specific ligands poliovirus receptor (PVR) (CD155) and Nectin-2 (CD112), found to be expressed on various acute leukemias." (PMID 31623224, 2019).
asthma (3 papers, 2021 to 2026). "Expression of CD226 (PPH4/PPH3 + PPH4 = 0.751) showed a significant colocalization association with asthma." (PMID 41573111, 2026). "To study the association between CD226 and asthma, we further detected CD226 levels on these Th cell subsets." (PMID 39349422, 2024). "In 2023, a study on the mechanism of asthma similarly demonstrated that down‐regulation of CD226 reduces allergic responses in the asthmatic airways, providing evidence for novel therapeutic approaches to asthma." (PMID 41573111, 2026). "Five druggable genes significantly associated with asthma were identified in whole blood (IRF1, OXER1, PSMA4, UNC13D, and HLA‐DRB1) and one in lung tissue (CD226)." (PMID 41573111, 2026). "A number of subsequent studies have also confirmed that CD226 can be a therapeutic target for asthma, providing a basis for subsequent studies." (PMID 41573111, 2026). "C57BL/6J WT mice with OVA-induced asthma were administered intraperitoneally with CD226-Fc fusion protein or IgG." (PMID 39349422, 2024). "To analyze the roles that CD226 plays in asthma pathogenesis, we used the OVA-induced allergic asthma model with the standard protocol." (PMID 39349422, 2024). "Herein, in addition to the attenuated Th2 response, we observed a reduction in Th17 cytokines in the lungs of both Cd226fl/flCd4-Cre and CD226-Fc-treated mice with OVA-induced asthma." (PMID 39349422, 2024). "Overall, this study revealed a unique role of CD226 in CD4+ T cell regulation in asthma pathogenesis." (PMID 39349422, 2024). "An experimental study found that CD226 deficiency in CD4 + T cells attenuated airway hyperresponsiveness in asthma in mice, thus validating that targeting CD226 may provide new ideas for the clinical treatment of asthma." (PMID 41573111, 2026). "Herein, we first evaluated the expression levels of CD226 on CD4+ T cells in patients with asthma." (PMID 39349422, 2024). "Furthermore, blocking CD226 signaling with a recombinant fusion protein attenuated asthma features in mice and achieved a good therapeutic effect." (PMID 39349422, 2024). "Allergic responses are triggered and maintained by an imbalance among CD4+ Th cells, specifically Th2 cells, therefore, we speculated that CD226 may play a regulatory role in the progression of asthma." (PMID 39349422, 2024). "Therefore, in addition to T cells, the CD226 signal blocked in other immune cells may be involved in improving asthma." (PMID 39349422, 2024). "Notably, administering CD226-Fc in vivo produced a slightly higher therapeutic effect with Cd226fl/flCd4-Cre mice among OVA-induced mice with asthma, as evidenced by a lower percentage of eosinophils in BALF and lower levels of OVA-specific IgE and IgG1 in serum." (PMID 39349422, 2024). "Our results revealed that the expression of CD226 was significantly increased in CD4+ effector T cells, especially in T helper (Th) 2 cells and Th17 cells in patients with asthma." (PMID 39349422, 2024). "Therefore, targeting CD226 may provide new insights into the clinical treatment of asthma." (PMID 39349422, 2024). "CCR9/CCL25 signal can interact with CD226 signaling to activate asthmatic NKT cells, leading to airway hyperresponsiveness and inflammation, aggravating asthma." (PMID 34490243, 2021). "However, the impact of CD226 on asthma was independent of Treg cell modulation." (PMID 39349422, 2024).
Crohn disease (3 papers, 2015 to 2025). A gastrointestinal disorder characterized by chronic inflammation involving all layers of the intestinal wall, noncaseating granulomas affecting the intestinal wall and regional lymph nodes, and transmural fibrosis. "Some genes of interest include CD226, a cell surface receptor involved in T cell adhesion and activation (associated with Crohn’s disease, RA, T1D and UC) which is upregulated in our coeliacs and was previously strongly associated with CD, falling however short of GWS (P = 10−7)." (PMID 26444573, 2015). "Seven shared risk genes (CD40, PTPN22, CD226, BATF, PRKCB, RasGRP1, and PTPN2) are involved in cytokine pathways linked to Crohn’s disease." (PMID 40839671, 2025).
cutaneous T-cell lymphoma (3 papers, 2022 to 2025). "A recent study investigated an intriguing association between a decreased surface expression of the CD226 receptor by CD8+ T- and NK cell populations and an elevated CD226 serum level in cutaneous T-cell lymphoma patients." (PMID 39796279, 2025). "A recent study reported that in cutaneous T-cell lymphoma, the reduced expression of CD226 by the CD8+ T and NK cell populations was in line with the higher level of sCD226 in the serum." (PMID 39125946, 2024).
fibrosarcoma (3 papers, 2014 to 2021). A malignant mesenchymal fibroblastic neoplasm affecting the soft tissue and bone. "The Ig-superfamily receptor DNAM-1 (CD226) also plays an important role in NK cell activation as methylcholanthrene-induced fibrosarcoma shows largely increased progression in DNAM-1-deficient mice." (PMID 35008589, 2021).
psoriasis (3 papers, 2015 to 2023). An autoimmune condition characterized by red, well-delineated plaques with silvery scales that are usually on the extensor surfaces and scalp. "In addition, rs763361 in CD226 has been associated with severity of psoriasis." (PMID 26613086, 2015). "Comparison between patients with type I psoriasis and patients with type II psoriasis revealed significant associations for the following genes: FCGR2A, TNFR1, CD226, PSORS6, TNFAIP3, HLA-C, TNF-α, and CCHCR1." (PMID 26613086, 2015). "Ours is the first study to identify an association between FCGR2A, TNFR1, CD226, TNFAIP3, and CCHCR1 and age at onset of psoriasis." (PMID 26613086, 2015).
pulmonary fibrosis (3 papers, 2012 to 2025). Chronic progressive interstitial lung disorder characterized by the replacement of the lung tissue by connective tissue, leading to progressive dyspnea, respiratory failure, or right heart failure. "Our data suggest that previously autoimmune-associated CD226 gene polymorphisms play a role in the SSc pulmonary fibrosis events in European Caucasian populations, and confirm CD226 as an important shared autoimmune factor in SSc." (PMID 22531499, 2012). "We report the association of a CD226 three-variant haplotype with SSc-related pulmonary fibrosis." (PMID 22531499, 2012). "Hence, we consider that the confirmation of CD226 as a pulmonary involvement marker might be valuable in the deciphering of the mechanisms that underlie the lung fibrosis process in SSc patients." (PMID 22531499, 2012). "Two genes, CD247 and CD226, are known to be involved in T-cell activation and function, but their specific role in the development of pulmonary fibrosis remains unclear." (PMID 40843700, 2025). "Our data suggest that the tested genetic variants do not individually influence SSc susceptibility but a CD226 three-variant haplotype is related with genetic predisposition to SSc-related pulmonary fibrosis." (PMID 22531499, 2012).
airway hyperresponsiveness (2 papers, 2024 to 2026). "The potential mechanisms of CD226 have been recently revealed in alleviating airway hyperresponsiveness via regulating type 2 innate lymphoid cell (ILC2) function, indicating the potential role of CD226 in allergic airway responses." (PMID 39349422, 2024).
allergic rhinitis (2 papers, 2022 to 2024). Inflammation of the nasal mucous membranes caused by an IgE-mediated response to external allergens. "Previously, we demonstrated the regulatory impact of CD226 on ILC2s in nasal mucosa during allergic rhinitis." (PMID 39349422, 2024).
Anxiety (2 papers, 2017 to 2020). Intense feelings of nervousness, tension, or panic often arise in response to interpersonal stresses. "Our recent study showed that CD226 deficiency improves cognitive functions and ameliorates anxiety-like behaviors in mice." (PMID 32104514, 2020). "Our previous studies found that CD226 is highly expressed on activated human endothelial cells 12 and CD226 deletion improves cognitive functions and ameliorates anxiety-like behaviors in mice." (PMID 32104514, 2020). "Our findings suggest that CD226 plays an important role in the modulation of cognition and anxiety in mice." (PMID 29299389, 2017). "Together, these studies suggest that CD226 plays an important role in cognition and anxiety in mice." (PMID 29299389, 2017). "In summary, CD226KO mice exhibited enhanced spatial learning and memory, and deletion of CD226 could also decrease the anxiety‐like behaviors." (PMID 29299389, 2017). "Moreover, the most robust behavioral indication for CD226 effect was observed in the OF test measuring anxiety‐like behaviors." (PMID 29299389, 2017). "The behavioral phenotypes of CD226KO mice in different experiments demonstrated that anxiety‐like behaviors could be genetically mapped through CD226." (PMID 29299389, 2017). "We also found that genetic deletion of CD226 resulted in decreased anxiety‐like behaviors." (PMID 29299389, 2017).
colitis (2 papers, 2022 to 2025). Inflammation of the colon. "A recent study demonstrated that the Myc inhibitor 10058-F4 partially reversed the detrimental effects of Treg cell-specific CD226 deficiency in the DSS-induced colitis model." (PMID 40118833, 2025). "Flow cytometry analysis showed that CD226 expression was increased in CD4+ T cells from spleens in DSS-induced colitis." (PMID 35844584, 2022). "Although CD226 expression was significantly higher in CD4+ T cells from the colon than that from the spleen, CD226 expression was no changed in CD4+ T cells from the colon of mice with DSS-induced colitis." (PMID 35844584, 2022).
diffuse large B-cell lymphoma (2 papers, 2017 to 2020). "To test this hypothesis, we evaluated CD226 mRNA expression in diffuse large B-cell lymphomas (DLBCLs) of the NF-κB-high, activated B-cell-like (ABC-DLBCL) and the NF-κB-low, germinal center B-cell-like (GCB-DLBCL) subsets." (PMID 29202043, 2017).
endometrial cancer (2 papers, 2022 to 2023). Primary or metastatic malignant neoplasm involving the endometrium (mucous membrane that lines the endometrial cavity). "Furthermore, in endometrial cancer, CAFs can decrease NK cells’ lytic potential through their downregulation of poliovirus receptor (PVR/CD155), a ligand of the activating DNAM-1/CD226." (PMID 36338519, 2022).
fibrosis (2 papers, 2012 to 2015). the formation of excess fibrous connective tissue in an organ or tissue in a reparative or reactive process. "Considering that fibrosis is a main hallmark of SSc, the specific association of CD226 with SSc fibrosis-positive patients might reflect the influence of this locus in diverse pathways." (PMID 22531499, 2012).
Hyperglycemia (2 papers, 2021 to 2025). An increased concentration of glucose in the blood. "The proportion of CD226+ B cells is independent of FBG levels in T2D patients or HC, suggesting that the elevated frequency of CD226+ B cells is mediated primarily by immune factors rather than hyperglycemia." (PMID 40957221, 2025).
liver cancer (2 papers, 2025). An epithelial or non-epithelial malignant neoplasm that arises from the liver. "For example, dysfunctional NK cells that express TIGIT in combination with lower levels of CD226 have been observed in liver cancer, correlate with disease prognosis and are increased in the periphery of hepatitis B-related HCC patients." (PMID 41451217, 2025). "In this study, we focused on the antitumor molecules (TRAIL, CD226, and NKG2D) that trigger different antitumor signals, and examined the expression status of these ligands in eight liver cancer cell lines." (PMID 39904787, 2025).
lymph node metastasis (2 papers, 2016 to 2024). "Further analysis demonstrated that the decrease in the percentage of CD226+ and CD96+ NK cells was associated with tumor histological grade and lymph node metastasis." (PMID 27626490, 2016).
neuromyelitis optica (2 papers, 2022 to 2025). A rare inflammatory disease of the central nervous system characterized mainly by attacks of uni- or bilateral optic neuritis (ON) and acute myelitis. "In neuromyelitis optica, CD226 overexpression on T regulatory type 1 cells correlates with disease severity, suggesting its role as a progression biomarker." (PMID 40723878, 2025).
primary biliary cholangitis (2 papers, 2020 to 2022). Primary biliary cholangitis (PBC) is a chronic and slowly progressive cholestatic liver disease of autoimmune etiology characterized by injury of the intrahepatic bile ducts that may eventually lead to liver failure. "The relationship between the cluster of differentiation 226 (CD226)/T cell Ig and ITIM domain (TIGIT) immune checkpoint and primary biliary cholangitis (PBC) pathogenesis is unknown." (PMID 32793241, 2020).
primary Sjögren's syndrome (2 papers, 2025). "Intriguingly, plasma soluble CD226 levels are reduced in primary Sjögren’s syndrome and inversely correlate with clinical manifestations and disease progression, indicating its diagnostic potential." (PMID 40723878, 2025). "Additionally, increased proportions of CD226+CD14+ monocytes have been reported in primary Sjögren’s syndrome patients, correlating with the severity of the disease." (PMID 40723878, 2025). "In primary Sjögren’s syndrome, CD226 expression is significantly altered in immune cells." (PMID 40723878, 2025).
prostate tumor (2 papers, 2015 to 2024). "Additionally, immune-based pathways that include genes crucial for the proliferation of lymphoid and T-cell progenitors, such as CD40 and CD226, were enriched in prostate tumors from AA men." (PMID 38566104, 2024).
renal cell carcinoma (2 papers, 2018 to 2021). "Tumor-infiltrating lymphocytes (TILs) from a variety of human tumors, including non-small cell lung cancer, renal cell carcinoma, and colorectal cancer, were analyzed for coexpression of TIGIT and CD226." (PMID 30400822, 2018). "A similar phenotype is observed in CD8+TILs from patients with renal cell carcinoma (RCC), colorectal cancer (CRC), and NSCLC that display upregulation of PD-1, TIGIT, Lag-3, and Tim-3 with reduced CD226 expression." (PMID 33670993, 2021).
sarcoidosis (2 papers, 2023 to 2024). Sarcoidosis is a multisystemic disorder of unknown cause characterized by the formation of immune granulomas in involved organs. "Among T cells, we found increased levels of IL-2R+ TIGIT+ LAG3+ CD4+ T cells in IPF, increased levels of CXCR3+ CD226+ CD4+ T cells in sarcoidosis, and increased levels of PD1+ TIGIT+ CD57+ CD8+ T cells in CTD-ILDs." (PMID 36949950, 2023). "Increase in CXCR3 CD226 CD4 in sarcoidosis • CXCL9 and CXCL11 are ligands of CXCR3, are IFN-inducible and found in granulomas.• CXCR3 expressing CD4+ T cells are recruited in granuloma.B cells: more prevalent in the BAL of sarcoidosis and CTD-ILD patients compared to IPF." (PMID 39896815, 2024). "This is the first report to mention CD226 expression in T cells from sarcoidosis." (PMID 36949950, 2023). "We showed increased levels of CXCR3+ CD226+ CD4+ T cells in sarcoidosis." (PMID 36949950, 2023). "We speculate that CD4 T cells migrating to the lungs through CXCR3 may be activated through CD226, potentially contributing to the pathogenesis of sarcoidosis." (PMID 36949950, 2023). "Using mass cytometry analysis of immune cell subsets in bronchoalveolar lavage fluid (BALF), the analysis of T and B cells revealed increased levels of CXCR3+ CD226+ CD4+ T cells and the presence of FCRL5+ B cells in sarcoidosis patients with advanced lung lesions." (PMID 39896815, 2024). "Cluster #5508, prevalent in sarcoidosis, was characterized by CD4+ CD226+ CXCR3+." (PMID 36949950, 2023).
skin tumors (2 papers, 2020 to 2025). "Therefore, the loss of CD8+CD226+ T cells might be a potential explanation for the poorer clinical outcomes of secondary skin cancer in CLL patients with a higher Rai stage." (PMID 39777847, 2025). "Another important study to consider in the future will be assessing the migratory capacity of CD8+CD226+ T cells to the skin and whether they contribute to the prevention of secondary skin tumors." (PMID 39777847, 2025). "However, further studies are needed to determine whether the preservation of CD8+CD226+ T cells alters the course of CLL disease and/or reduces secondary skin tumors." (PMID 39777847, 2025). "Interestingly, we found Pd‐1 and its ligands Pd‐l1 and Pd‐l2 as well as Tigit, Tim3, and Cd226 to be significantly upregulated in skin tumors, whereas Lag3 and Cd96 were not significantly changed compared to control skin." (PMID 32615027, 2020).
type 2 diabetes mellitus (2 papers, 2016 to 2021). A type of diabetes mellitus that is characterized by insulin resistance or desensitization and increased blood glucose levels. "Here, we evaluated a possible role for CD226 in inhibiting glucose uptake in isolated human umbilical vein endothelial cells (HUVECs) and in wild-type (WT) and CD226 knockout (KO) mice with high-fat diet (HFD)-induced type 2 diabetes (T2DM)." (PMID 26910838, 2016).
allergic asthma (1 paper, 2024). A asthma with a basis in a pathological type I hypersensitivity reaction. "Next, we used a conditional knockout (CKO) strategy and observed that the loss of CD226 in CD4+ T cells alleviated ovalbumin (OVA)-induced allergic asthma in mice, and CD226 played a critical role in regulating CD4+ T cell apoptosis." (PMID 39349422, 2024). "This study demonstrated the regulatory role of CD226 in allergic asthma by modulating the apoptosis of CD4+ T cells." (PMID 39349422, 2024). "In the present study, our data for the first time demonstrated that CD226, as a pivotal costimulatory molecule present on T cells, can potentially serve as a novel therapeutic target for allergic asthma." (PMID 39349422, 2024). "Here, we investigated the molecular role and clinical significance of CD226, a costimulatory molecule of T lymphocytes, in the development of allergic asthma." (PMID 39349422, 2024). "We found that CD226 deficiency in CD4+ T cells mitigated lung inflammation, IgE production, and eosinophil infiltration and reduced airway remodeling in experimental allergic asthma." (PMID 39349422, 2024). "Finally, we investigated the effects of the recombinant CD226 fusion protein (CD226-Fc) on airway inflammation and remodeling in mice with allergic asthma." (PMID 39349422, 2024). "In addition, we demonstrated that the CD226-Fc recombinant protein exhibited a protective effect against allergic asthma in mice." (PMID 39349422, 2024). "Blocking CD226 signaling showed an obvious therapeutic effect on allergic asthma in mice." (PMID 39349422, 2024). "Moreover, CD4+ T cell-specific Cd226-knockout mice were generated and together with littermates were challenged with ovalbumin (OVA) to establish a model of allergic asthma." (PMID 39349422, 2024).
Arthritis (1 paper, 2015). Inflammation of a joint. "Despite some clues suggesting a role of DNAM-1 in arthritis, these complementary approaches demonstrate no contribution of CD226/DNAM-1 in the arthritic phenotype." (PMID 25685070, 2015).
bladder tumors (1 paper, 2026). "TIGIT is an inhibitory receptor expressed on T cells and natural killer cells and regulates anti-tumor immunity through competition with CD226 for binding to CD155, and increased expression of TIGIT in bladder tumors is associated with impaired effector function." (PMID 41590518, 2026).
Burkitt lymphoma (1 paper, 2017). A rare form of malignant mature B-cell non-Hodgkin lymphoma. "Interestingly, CD40 ligation is insufficient in inducing CD226 expression in proliferating B cells, while the viral homologue of CD40, LMP1, sufficiently induces CD226 in the non-EBV Burkitt’s lymphoma line, BL41." (PMID 29202043, 2017).